BRCA2 (BRCA2 DNA repair associated)
Diseases named in the same sentence as BRCA2 in open-access papers (continued):
Sharing a sentence is not in itself a finding about the gene and the disease.
angiosarcoma (2 papers, 2018 to 2022). A malignant tumor arising from the endothelial cells of the blood vessels. "The BRCA2 (c.1909+22delT) variant was found in 12 of the 13 radiation-associated angiosarcomas in the current study." (PMID 29515789, 2018). "In another study, 3 of 7 cases of radiation-induced angiosarcoma contained BRCA1 or BRCA2 mutations." (PMID 29515789, 2018).
Ataxia (2 papers, 2012 to 2024). Ataxia refers to impaired coordination of voluntary muscle movement. "In addition, severe ataxia was not reported in the BRCA2 deficient mice, while BCCIP-CKD mice displayed severe ataxia." (PMID 22292003, 2012).
autism (2 papers, 2010 to 2019). Persistent deficits in social interaction and communication and interaction as well as a markedly restricted repertoire of activity and interest as well as repetitive patterns of behavior. "Important candidate genes (e.g., PTEN, NF1, and BRCA2) are found meeting criteria clearly associated with predisposition to cancer such as colorectal, other gastrointestinal tumors, and breast reported in the top seven autism and cancer-associated diseases." (PMID 30866437, 2019). "In the BRCA2 region, we observed a significant excess of sharing amongst both Ashkenazi (n = 304) and non-Jewish (n = 1331) individuals compared to samples from an autism study (n = 808) suggesting common founders for BRCA2 mutations." (PMID 21060860, 2010).
bladder (urothelial) cancer (2 papers, 2021).
bone metastasis (2 papers, 2023). Transfer of a neoplasm from its primary site to bones. "As observed in our study, the two patients with PC had the same BRCA2 pathogenic variant, one (Patient D) with Gleason 8 and bone metastasis at presentation and the other one (Patient I) with biochemical relapse treated with salvation radiation." (PMID 37347260, 2023).
clear cell ovarian cancer (2 papers, 2018 to 2020). "Herein we present the provincial statistics on uptake of index BRCA1 and BRCA2 genetic testing in BC before and after the 2010 campaign comparing rates of testing between serous cancer patients and endometrioid and clear cell ovarian cancer patients." (PMID 29506471, 2018).
cognitive decline (2 papers, 2019 to 2025). "Impaired DNA repair mechanisms, such as those involving BRCA-2 and PARP-1, exacerbate neuronal damage and cognitive decline." (PMID 40282301, 2025).
Erythema nodosum (2 papers, 2018 to 2023). An erythematous eruption commonly associated with drug reactions or infection and characterized by inflammatory nodules that are usually tender, multiple, and bilateral. "This case represents a patient with metastatic breast cancer and germline BRCA2 mutation who developed erythema nodosum after initiation of therapy with olaparib capsules." (PMID 30050710, 2018).
female infertility (2 papers, 2019 to 2024). Diminished or absent ability of a female to achieve conception. "Both MCM8 and BRCA2 have been shown to be associated with meiosis and female infertility, and STAG3 is a meiosis-specific gene involved in female infertility." (PMID 31803224, 2019).
Luminal B (2 papers, 2022). "For instance, BRCA1-633delC was detected with relatively higher prevalence in patients with TNBC, whereas BRCA2-1466delT was found mainly in Luminal B tumors, but not in TNBC patient." (PMID 35858847, 2022).
malignant peripheral nerve sheath tumor (2 papers, 2016 to 2020). Malignant peripheral nerve sheath tumor (MPNST) is a rare and often aggressive soft tissue sarcoma occurring in a wide range of anatomical sites. "BRCA2 expression was associated with shorter survival in malignant peripheral nerve sheath tumors." (PMID 27643881, 2016).
meningioma (2 papers, 2018 to 2024). A generally slow growing tumor attached to the dura mater. "Specifically, the classification of the BRCA2 (p.E51K) mutation as a driver remains inconclusive, necessitating additional studies to explore its functional impact in meningiomas." (PMID 39935847, 2024). "The interpretation of BRCA2 (p.E51K) as a driver mutation in this context warrants careful consideration, especially given that NF2 is a well-recognized primary driver in meningiomas." (PMID 39935847, 2024). "Although not well described in meningioma, BRCA2 mutations are predicted to be a biomarker of drug response to PARP inhibition." (PMID 39935847, 2024). "Our analysis also suggests that the presence of BRCA2 may represent a secondary or potentially modifying genetic event; however, this interpretation warrants cautious consideration, particularly given the established role of NF2 mutations in meningioma." (PMID 39935847, 2024). "While our analysis identified a BRCA2 (p.E51K) mutation present alongside NF2 gene loss in the same cancer clone across all tumor samples, it is important to acknowledge that the evidence supporting BRCA2 (p.E51K) as a driver mutation in meningioma is not well-established." (PMID 39935847, 2024).
mucinous neoplasm (2 papers, 2021 to 2023). "Two long-term BRCA2 survivors both diagnosed at aged 32 had mucinous tumours (the remaining histologies were high-grade serous: BRCA1=2, adenocarcinoma not otherwise specified BRCA1=5; endometrioid BRCA2=1), raising doubts as to whether these were HRD-driven tumours." (PMID 36894311, 2023).
mucosal (2 papers, 2021). "However, only BRCA2 alterations correlated with increased mean severity in all four clinical toxicity categories compared to patients with wild-type BRCA2: mucositis (31.82%) early dysphagia (45%), xerostomia (37%), and to a lesser extent late dysphagia (4.57%)." (PMID 34001187, 2021).
multiple endocrine neoplasia syndrome type 1 (2 papers, 2016 to 2022). "Only 10% of PDACs are linked to genetic mutations such as BRCA2, STK11/LKB1, CFTR, and PRSS1 or to familial syndromes such as Von Hippen-Lindau disease (VHL), multiple endocrine neoplasia syndrome type 1 (MEN-1), and neurofibromatosis type 1 (NF-1)." (PMID 36611999, 2022).
myelodysplastic syndrome (2 papers, 2023 to 2025). A clonal hematopoietic disorder characterized by dysplasia and ineffective hematopoiesis in one or more of the hematopoietic cell lines. "Overall, 16 patients (17.2%) had pathogenic variants, including FANCA, BRCA2, PMS2, ELANE, G6PC3 and VPS13B in patients with idiopathic neutropenia, and GATA2 in patients with suspected myelodysplastic syndrome." (PMID 40358701, 2025).
myxofibrosarcoma (2 papers, 2016 to 2025). A malignant fibroblastic neoplasm arising from the soft tissue. "Of note, a patient with myxofibrosarcoma who had an ongoing deep and sustained response harbored a mutation in PALB2, which is involved in the recruitment of BRCA2 and RAD51 to DNA breaks in the homologous recombination pathway." (PMID 41145467, 2025).
nasopharyngeal carcinoma (2 papers, 2021 to 2023). A carcinoma arising from the nasopharyngeal epithelium. "A similar study in a nasopharyngeal carcinoma (NPC) (CNE2RR) cell line induced the expression of NFBD1, BRCA1, BRCA2, RPA1, and RAD51 proteins widely associated with HR and radioresistance." (PMID 34900673, 2021). "However, it has also been reported that an increase in the gene expression level of DDR genes may lead to resistance to cisplatin chemotherapy, while the overexpression of BRCA1, BRCA2, RAD51 and RPA1 has been observed in hypopharyngeal and nasopharyngeal carcinoma cells resistant to radiotherapy." (PMID 37740039, 2023).
neuroendocrine carcinoma (2 papers, 2024 to 2025). A malignant neuroendocrine neoplasm composed of cells containing secretory granules that stain positive for NSE and chromogranin. "While germline BRCA2 mutations are well-established drivers of breast, ovarian, prostate, and pancreatic cancers, their role in neuroendocrine carcinoma remains less defined, although they have been reported in prostate, gallbladder, and ovarian NECs." (PMID 41487567, 2025).
pancreatitis (2 papers, 2023 to 2024). Inflammation of the pancreas. "They include DNA damage response and DNA repair genes (ATM, BRCA1, BRCA2, and POLQ), pancreatitis gene (SPINK1) and cell apoptosis gene (CASP8)." (PMID 37234870, 2023).
papillary thyroid cancer (2 papers, 2011 to 2025). "Background/Objectives: We sought to evaluate the association between the risk of papillary thyroid carcinoma (PTC) and single-nucleotide polymorphisms (SNPs) of breast cancer genes 1 (BRCA1) and 2 (BRCA2)." (PMID 40361383, 2025). "However, the association of BRCA1/BRCA2 genetic polymorphism with the risk of papillary thyroid carcinoma (PTC) has not been thoroughly investigated." (PMID 40361383, 2025).
Pca (2 papers, 2019 to 2023). "In general, BRCA2 carriers are at a two to five times higher risk of PCa compared to men in the general population." (PMID 36612302, 2023). "Ashkenazi Jewish ancestry was associated with BRCA1/2 variants in men with PCa, with a prevalence of BRCA2 (1–3%)." (PMID 36612302, 2023). "We identified 46 BRCA1 and 68 BRCA2 variants in PCa Ashkenazi patients, and 108 BRCA1 and 402 BRCA2 variants in non-Ashkenazi patients." (PMID 36612302, 2023). "This meta-analysis suggests that BRCA1 and BRCA2 occur in PCa Ashkenazi with a similar prevalence; moreover, the prevalence of germline founder variants presents a different frequency in PCa in comparison to BC, in particular with 6176delT (BRCA2) and 185delAG (BRCA1) variants." (PMID 36612302, 2023). "Genetic screening demonstrated a strong association with germline BRCA2 mutations and PCa risk." (PMID 36612302, 2023). "They estimated a cumulative risk of developing PCa by age 85 years of 29% (95% CI 17–45%) for BRCA1 and of 60% (95% CI 43–78%) for BRCA2 carriers." (PMID 36612302, 2023). "In comparison to BC, the founder 6174delT (BRCA2) and 185delAG (BRCA1) variants were more prevalent in PCa." (PMID 36612302, 2023). "There are several genes associated with hereditary PCa, with variable frequencies: HOXB13 (0.6–6.25%), BRCA2 (1.2–5.3%), CHEK2 (1.6–2.7%), ATM (1.6–2.7%), MMR (0.7–1.74%), BRCA1 (0.9–1.25%), PALB2 (0.4- 0.5%), BRP1, and NBS1 (0.1–0.2%)." (PMID 36612302, 2023). "Our results demonstrate a similar prevalence of BRCA1 and BRCA2 in PCa Ashkenazi Jewish patients." (PMID 36612302, 2023). "We were not able to quantify the real PCa risk in BRCA1 and BRCA2 due to the lack of information about healthy carriers." (PMID 36612302, 2023). "Considering the overall PCa patients, in Ashkenazi patients we identified a total of 46 (40.4%) germline BRCA1 (3,490 PCas) and 68 (59.6%) BRCA2 (3,527 PCas) variants, and in non-Ashkenazi patients 108 (21.2%) BRCA1 (23,767 PCas) and 402 (78.8%) BRCA2 (21,106 PCas) variants." (PMID 36612302, 2023).
penile cancer (2 papers, 2024). A primary or metastatic malignant neoplasm that affects the penis. "The study is the first and only known evaluation of the germline mutations in patients with penile cancer, as well as the only known study to identify potentially clinically actionable mutations in those with BRCA2 mutations." (PMID 39882447, 2024). "Although several case reports have demonstrated potential clinical efficacy in patients whose tumors harbor EGFR or BRCA2 mutations, prospective data lacks in oncogenic driver mutated penile cancer." (PMID 39882447, 2024). "This is the first report of penile cancer with BRCA2 mutation, receiving a combination treatment with olaparib and experiencing a benefit for 9 months." (PMID 38336701, 2024).
penile squamous cell carcinoma (2 papers, 2024 to 2025). "Despite the rarity of penile squamous cell carcinoma, BRCA1 and BRCA2 mutations were identified in both cases analyzed, suggesting homologous recombination deficiency and potential sensitivity to PARP inhibitors." (PMID 41395625, 2025).
pharyngeal cancer (2 papers, 2021 to 2025). "Only one study focused on pharyngeal cancer and showed that BRCA2 increased the incidence of this cancer." (PMID 34577828, 2021).
pleural mesothelioma (2 papers, 2022 to 2023). A neoplasm that arises from the mesothelial cells of the pleura. "In our cohort, BRCA2 alterations were detected in 2.5% of pleural mesothelioma and in 1.7% of peritoneal mesothelioma tumours, while a recent study detected BRCA2 alterations in 3 out of 37 pleural mesothelioma patients." (PMID 36138075, 2022).
Premature ovarian insufficiency (2 papers, 2019 to 2021). Amenorrhea due to loss of ovarian function before the age of 40. "Specifically, mutations in FANCM as well as FANCA, BRCA1/FANCS and BRCA2/FANCD1 are associated with premature ovarian insufficiency." (PMID 33500205, 2021). "Subsequently, additional compound heterozygous BRCA2 mutations were identified in Chinese and Italian patients with premature ovarian insufficiency, which expands the phenotypic spectrum associated with biallelic hypomorphic BRCA2 variants." (PMID 31209201, 2019).
rheumatoid arthritis (2 papers, 2018 to 2025). A chronic, systemic autoimmune disorder characterized by inflammation in the synovial membranes and articular surfaces. "We saw an increase in expression of 3 DDRFs including Rad51 (Rheumatoid arthritis), XRCC4 (lesional skin), and BRCA2 (asthma) while 1DDRFs was downregulated." (PMID 29867559, 2018).
small cell lung carcinoma (2 papers, 2017 to 2024). Small cell lung cancer (SCLC) is a highly aggressive malignant neoplasm, accounting for 10-15% of lung cancer cases, characterized byrapid growth, and early metastasis. "To address whether acetaldehyde toxicity can be extended to other cell lines, we examined the response to this compound in human H1299 non‐small cell lung carcinoma cells expressing a doxycycline (DOX)‐inducible BRCA2 shRNA (BRCA2shDOX)." (PMID 28729482, 2017).
uterine fibroids (2 papers, 2023 to 2024). "Hysterectomy was performed in five of six BRCA1 pathological variants (Patient 1 of the BRCA1 pathological variant group had already had a hysterectomy due to a history of uterine fibroids) and 5 of 12 BRCA2 pathological variants." (PMID 36849964, 2023).
von Hippel-Lindau syndrome (2 papers, 2008 to 2020). "The largest number of concurrent CVs was observed in the VHL gene (von Hippel-Lindau syndrome, MIM# 193300), followed by BRCA1/BRCA2 (hereditary breast cancer syndrome, MIM# 113705, 600185)." (PMID 18974781, 2008).
adenosarcoma (1 paper, 2017). A low grade malignant neoplasm characterized by the presence of a benign epithelial component (tubular and cleft-like glands) and a low grade sarcomatous component that contains varying amounts of fibrous and smooth muscle tissues. "Several cancer genes rarely mutated in adenosarcomas, such as DICER1 (11%), FGFR2 (11%), and BRCA2 (5%), were not mutated in any of the PTs analyzed." (PMID 28267263, 2017).
Alpha-thalassemia (1 paper, 2024). Alpha-thalassemia is an inherited hemoglobinopathy characterized by impaired synthesis of alpha-globin chains leading to a variable clinical picture depending on the number of affected alleles.
ameloblastoma (1 paper, 2025). The most common odontogenic tumor, arising from the epithelial component of the embryonic tooth and usually affecting the molar-ramus region of the mandible or maxilla. "Additional studies showed gene expression profile differences between plexiform and follicular ameloblastomas, with follicular ameloblastomas expressing variants of BRAF, KMT2D, and ABL1, while plexiform ameloblastomas expressed variants of ALK, BRAF, KRAS, KMT2D, SMO, KMT2A, and BRCA2." (PMID 38607614, 2025).
amenorrhea (1 paper, 2021). The absence of menses in a woman who has achieved reproductive age. "The authors reported a statistically significantly higher proportion of chemotherapy-induced amenorrhea among BRCA2 pathogenic variant carriers than BRCA1 ones." (PMID 34503502, 2021). "Even excluding patients taking tamoxifen (most numerous among the BRCA2 cohort), the likelihood of chemotherapy-induced amenorrhea remained significantly different compared to patients who did not undergo chemotherapy." (PMID 34503502, 2021).
anal carcinoma (1 paper, 2022). "A study evaluating a cohort of BRCA1 or BRCA2 pathogenic variant carriers mostly of Ashkenazy ancestry concluded that they may be prone to developing anal carcinoma and left-sided mucinous histology CRC." (PMID 35280729, 2022).
aplastic anemia (1 paper, 2024). Anemia resulting from bone marrow failure (aplastic or hypoplastic bone marrow). "We are reporting an interesting case of olaparib-associated aplastic anemia in a 75-year-old man with BRCA2-positive metastatic castrate-resistant prostate cancer." (PMID 39175508, 2024).
Arrhythmia (1 paper, 2017). Any cardiac rhythm other than the normal sinus rhythm. "In addition, 21 of 232 (9.1%) BRCA1 carriers and 13 of 159 (8.2%) of BRCA2 carriers reported arrhythmias." (PMID 28157161, 2017). "In addition, 9.1% of BRCA1 carriers and 8.2% of BRCA2 carriers reported arrhythmias." (PMID 28157161, 2017).
astroblastoma (1 paper, 2025). "We presented a case of high-grade pediatric MN1-altered, BRCA2-mutated astroblastoma managed with maximal safe resection, adjuvant proton beam therapy including craniospinal irradiation, chemotherapy, and subsequent salvage Gamma Knife radiosurgery for residual disease." (PMID 40978059, 2025).
autoimmune conditions (1 paper, 2025). "For patients with clinically significant autoimmune conditions, early comprehensive genomic profiling may help identify non-immunotherapy systemic options, such as PARP inhibition in the presence of BRCA2 or other HRD-associated alterations." (PMID 41487567, 2025).
autoimmune disease (1 paper, 2025). A disorder resulting from loss of function or tissue destruction of an organ or multiple organs, arising from humoral or cellular immune responses of the individual to their own tissue constituents. "We report the successful off-label use of the PARP inhibitor talazoparib in a patient with metastatic, germline BRCA2-mutated rectal NEC who had a contraindication to standard immunotherapy due to underlying autoimmune disease." (PMID 41487567, 2025).
benign breast tumours (1 paper, 1996). "For BRCA2 (D13S260, D13S267, D13S171) losses could be detected in 108 IDCs in 30-38%, in 19 ILCs in 17-39% depending on the marker applied, but not in benign breast tumours." (PMID 8630282, 1996).
bipolar disorder (1 paper, 2020). A disorder of the brain that causes unusual shifts in mood, energy, activity levels and the ability to carry out day-to-day tasks. "Chromosome 13 is also responsible for type 2 breast cancer (BRCA2) and contains the DAOA locus associated with bipolar disorder and schizophrenia, among many other genetic diseases." (PMID 32244767, 2020).
carcinoid tumor (1 paper, 2019). A slow growing neuroendocrine tumor, composed of uniform, round, or polygonal cells having monotonous, centrally located nuclei and small nucleoli, infrequent mitoses, and no necrosis. "The present case report highlights a possible association between carcinoid tumors and BRCA2 gene mutation." (PMID 31039815, 2019).
cardiac hypertrophy (1 paper, 2026). "Cardiac hypertrophy triggered by Ang II in mice was significantly attenuated upon BRCA2 overexpression." (PMID 41625597, 2026). "BRCA2 alleviated cardiac hypertrophy via attenuation of inflammation and apoptosis." (PMID 41625597, 2026).